HSF2 (heat shock transcription factor 2)
Diseases named in the same sentence as HSF2 in open-access papers (continued):
Sharing a sentence is not in itself a finding about the gene and the disease.
tumor (continued). "Second, the property of HSF2 to be dynamically degraded or stabilized may represent an advantage for tumor cells to adjust to abrupt proteotoxic conditions that they undergo, and our findings might provide a better understanding of this dynamics in the future." (PMID 40318841, 2025). "Using HSF1 and/or HSF2 knockout cell lines, dysregulated responses to nutrient stress could be observed, as well as a reduction in tumor progression, making HSF2 a critical co-factor of HSF1." (PMID 36765939, 2023). "However, HSF2 has appeared to decrease in a wide range of cancers and act as a tumor suppressor 22,23." (PMID 33390814, 2021). "Altogether, these previous studies suggest that HSF2 may function as an oncogenic or tumor-suppressing gene in different tumors." (PMID 35087869, 2021). "Moreover, marked upregulation of HSF2 expression was detected in 50 paired tumor samples and adjacent normal samples." (PMID 34917120, 2021). "Moreover, the results from the UALCAN database suggested that HSF2 overexpression was significantly correlated with a shorter OS for patients with HCC of different tumor grades and sexes." (PMID 34917120, 2021). "Conversely, engineering tumor-specific macrophages and Th cells by modulating HSF2 expression may also be a promising strategy to increase the efficacy of immunotherapy." (PMID 35087869, 2021). "Moreover, ALG3 knockdown reduces tumor growth and HSF2 expression levels, indicating a feedback loop between HSF2 and ALG3." (PMID 34917120, 2021). "Furthermore, we investigated the effect of HSF2 expression on immune checkpoint blockade therapy in both TCGA and ICGC datasets and found that the HSF2 high-expression group exhibited a higher TIDE (tumor immune dysfunction and exclusion) score, which indicates a worse response to immunotherapy." (PMID 34917120, 2021). "HSF2 expression was significantly associated with the expression of most gene markers of T cells, CD8+ T cells, B cells, monocytes, tumor-associated macrophages (TAMs), M1 and M2 macrophages, neutrophils, NK cells and dendritic cells in patients with HCC after adjusting for tumor purity." (PMID 34917120, 2021). "Therefore, it is possible that HSF2 can counteract tumor progression in certain cases of ESCC." (PMID 32408596, 2020). "In Huh-7 and SMMC-7721 cells, HSF2 was shown to interact with euchromatic histone lysine methyl transferase 2 (EHMT2) in order to epigenetically silence the gene encoding fructose-bisphosphatase 1 (FBP1), which is a tumor suppressor and negative regulator of aerobic glycolysis." (PMID 32408596, 2020). "Therefore, the interplay between HSF1 and HSF2 may regulate their function and play an important role on tumor progression by activating target genes." (PMID 20537126, 2010). "In vivo, therapeutic immunization with the minimal epitope Hsf2 p.K72N elicited an enrichment of 47BE7+ CD8+ T cells amongst tumour-infiltrating lymphocytes (TILs) and delayed tumour growth." (PMID 38459027, 2024). "We selected H2-Db/Hsf2 p.K72N68-76 and 47BE7 for characterization due to demonstrable in vitro and in vivo activity in a challenging tumour model." (PMID 38459027, 2024). "Knockdown of TUG1 increases blood-tumor barrier (BTB) permeability via binding to miR-144 and reducing tight junction protein expression in endothelial cells through targeting HSF2." (PMID 28717243, 2017). "Importantly, while vaccination with Hsf2 p.K72N68-76 peptide suppressed tumour growth, ACT shows significant anti-tumour effect only with Hsf2 p.K72N68-76 overexpressed by B16F10 cells." (PMID 38459027, 2024). "Notably, HSF1, HSF2, and HSF4 were upregulated in HCC, KIRP, and COAD, with HSF1 being upregulated in most tumor types." (PMID 39248163, 2024). "Among them, only the TCR targeting H2-Db-restricted Hsf2 p.K72N (‘p’ indicating peptide residue) confers specific recognition of the B16F10 cells in vitro and demonstrates anti-tumour effect in vivo, albeit dependent upon sufficient tumour expression of neoAg Hsf2 p.K72N." (PMID 38459027, 2024).
tumor (continued). "Hence, there is a great need for comprehensive analyses of HSF2 and HSF4 expression in different tumor types." (PMID 32408596, 2020). "Unlike HSF1, the role of HSF2 in tumor progression is unclear." (PMID 20537126, 2010).
respiratory diseases (1 paper, 2019). "All studied isolates from saigas contained a combination of genes associated with respiratory diseases of other animals (ptfA, ompA, ompH, oma87, plpB, fimA, hsf-2, pfhA, exbB, tonB, hgbA, fur, nanB, nanH and pmHAS)." (PMID 30744550, 2019).
HSF2 also shares sentences with these, for which no sentence is quoted: neurodegenerative disease (3 papers); cervical cancer (2); infection (2); inflammatory bowel disease (2); neurodevelopmental disorder (2); Rubinstein-Taybi syndrome (2); Salmonella Infections (2); shigellosis (2); small cell lung carcinoma (2); viral infection (2); Angelman Syndrome-like (1); asthenozoospermia (1); attention deficit-hyperactivity disorder (1); Behcet disease (1); bipolar disorder (1); cardiomyopathy (1); cardiovascular diseases (1); cataract (1); cholangiocarcinoma (1); chronic myeloid leukemia (1); colon adenocarcinoma (1); colon cancer (1); colorectal adenocarcinoma (1); Crohn disease (1); dilated cardiomyopathy (1); embryonic carcinoma (1); endometrial cancer (1); escherichia coli infection (1); esophageal carcinoma (1); Fanconi anemia (1).
A further 14 diseases each share a sentence with HSF2 in 1 paper.